CTLA4 (cytotoxic T-lymphocyte associated protein 4)
Diseases named in the same sentence as CTLA4 in open-access papers (continued):
Sharing a sentence is not in itself a finding about the gene and the disease.
cancer (continued). "Immune checkpoint therapy has become an important pillar in cancer therapy with mAbs targeting CTLA-4 and PD-1/PD-L1 showing clinical benefit in patient subgroups with solid tumors." (PMID 31569553, 2019). "The Nobel Prize in Physiology or Medicine 2018 was awarded for the discovery of cancer therapy by the inhibition of CTLA-4 and PD-1." (PMID 30917623, 2019). "Immune checkpoint blockade including antibodies targeting cytotoxic T lymphocyte antigen-4 (CTLA-4) and programmed death-1 (PD-1) proteins, have demonstrated anti-cancer activity in multiple cancer types." (PMID 31218069, 2019). "To test this, we performed TCRB sequencing on the same peripheral blood mononuclear cells (PBMC) from individuals with cancer receiving anti-CTLA-4 or anti-PD-1 using an Illumina-based approach (Sequenta) and an Ion Torrent-based approach (Oncomine TCRB-LR)." (PMID 31993050, 2019). "Cancer patients who experienced severe IrAEs under CTLA4 blockade developed higher numbers of newly expanded T-cell clones." (PMID 31275310, 2019). "Currently, CAR-T cells, which are designed to secrete PD-1, CTLA-4 or PD-L1 antibodies, have entered clinical trials for cancers expressing MUC1, EGFR, EGFRVIII, and mesothelin." (PMID 31379886, 2019). "Six drugs targeting PD-1 or its ligand PD-L1 and one drug targeting CTLA-4 have been approved for treatment of different types of cancers and several others are in advanced stages of development." (PMID 31196207, 2019). "Patients with HIV infection and cancer also demonstrate high expression of CTLA-4 and PD-1 on their lymphocytes." (PMID 31113482, 2019). "The role of cytotoxic T lymphocyte antigen 4 (CTLA–4) as a molecular target for cancer immunotherapy was shown for the first time in 1996." (PMID 31137683, 2019). "Programmed cell death protein 1 (PD-1) and cytotoxic T-lymphocyte antigen 4 (CTLA-4) play a crucial role in anti-cancer immunity." (PMID 29486725, 2018). "As more than half of the cancers were EBV-associated, the failure to control oncogenic viruses seems to be part of the CTLA-4-insufficient phenotype." (PMID 30250467, 2018). "Cancers utilize these immune checkpoints as an escape mechanism by binding to the CTLA-4 and PD receptors more competitively and stronger, thus inhibiting the cytotoxic T-Cell and immune response and avoiding detection and/or destruction by the immune system." (PMID 29644213, 2018). "In veterinary medicine, previous studies have revealed that these immune checkpoint molecules including PD-1 and CTLA-4 are also highly expressed, with PD-L1 being up-regulated, in several cancers." (PMID 30040869, 2018). "The first of these checkpoint inhibitory molecules to be targeted for blocking in therapy, and is now FDA approved for cancer therapy, is CTLA-4." (PMID 29843813, 2018). "While the clinical successes of immunotherapeutic antibodies targeting PD-1 and CTLA-4 have revolutionized the treatment of cancer, a majority of patients still fail to achieve objective responses." (PMID 30400835, 2018). "Although PD-1 and CTLA-4 targeting therapies have been able to increase average life expectancy for cancer patients, mortality remains high among advanced-stage patients, highlighting the need for further innovation in the field." (PMID 29644214, 2018). "Check point inhibitors targeting CTLA4 and PD-1/PD-L1 axis are immunotherapeutic agents currently available to treat a variety of cancers." (PMID 30338242, 2018). "Persistent Foxp3 expressors highly expressed the coinhibitory/costimulatory molecules Ctla4, Icos and Tigit, and the serine protease Gzmb, all of which are involved in cancer immunity." (PMID 29991564, 2018). "Despite these differences, inhibitors of both PD-1/PD-L1 and CTLA-4 are able to (re-)activate T cells to attack cancer cells and have shown unprecedented durable responses in many cancer types." (PMID 30692993, 2018).
cancer (continued). "Cancer immunotherapy is currently focused on targeting immune inhibitory checkpoints that control T cell activation, such as CTLA-4 and PD-140,42,43,65–67." (PMID 29467463, 2018). "Although the relative importance of the immune checkpoint and regulatory depletion mechanisms for therapeutic efficacy is still under active debate, blocking CTLA-4 in cancer enhances T-cell activation, but can also lead to autoimmune responses." (PMID 30627131, 2018). "Recent advances in cancer immunotherapy, including the development of immune checkpoint blockades (ICBs), such as those targeting PD-1, PD-L1, and CTLA-4, have resulted in a paradigm shift in cancer treatment." (PMID 30314524, 2018). "Immune checkpoint inhibitors, such as anti-CTLA-4, anti-PD-1, and anti-PD-L1, can enhance antitumor immunity and mediate cancer regressions in many types of cancers." (PMID 29707526, 2018). "Here we leverage the low base substitution error rate of the Ion Torrent platform to evaluate convergence as a predictive biomarker for response to anti-CTLA-4 monotherapy in a set of 22 individuals with cancer." (PMID 30400835, 2018). "The 2018 Nobel Prize in Physiology or Medicine was recently given to James P. Allison and Tasuku Honjo for their discovery and contribution in cancer immunotherapy correlated with CTLA-4 and PD-1." (PMID 30547012, 2018). "The reported clinical success of targeting the T cell immune checkpoint receptors PD-1 or CTLA4 by antibodies blockade in advanced stages of cancers has demonstrated the importance of immune modulation." (PMID 29974338, 2018). "All of these findings suggest that current efforts to translate Tim-3 as a target for immunotherapy of cancer will be more complicated than other targets with more limited expression (for example, CTLA-4 and PD-1)." (PMID 29560265, 2018). "On the other hand, CTLA-4 is constitutively expressed in T cells during chronic infection and cancer due to chronic antigen exposure." (PMID 29515971, 2018). "Now several clinical trials are underway for H&N cancers to explore combinatorial approaches to inhibit not only PD-1/PD-L1 signaling but also in conjunction with anti-CTLA-4 agents." (PMID 29743117, 2018). "Monoclonal antibodies against PD-1 (nivolumab and pembrolizumab), PD-L1 (atezolizumab), and CTLA-4 (ipilimumab) are currently used for the treatment of advanced stage cancers and have demonstrated notable clinical efficacy." (PMID 29486725, 2018). "Therapeutic strategies targeting the CTLA-4 or PD-1 pathway restore T cell function in the cancer microenvironment and lead to durable clinical responses in various cancer types." (PMID 30250471, 2018). "The anti-CTLA-4 blocking antibody ipilimumab was the first immune checkpoint inhibitor to be tested and approved for the treatment of cancer patients." (PMID 29644214, 2018). "Antibodies targeting CTLA-4, PD-1, and PD-L1 are currently licensed as monotherapies for various type of cancer." (PMID 29482595, 2018). "Of note, the clinical successes of immune checkpoint blockade, such as PD-1 and CTLA-4, represent a landmark event in cancer immunotherapy development." (PMID 29735917, 2018). "In cancer patients, it has been demonstrated that upon anti-CTLA-4 treatment, the number of circulating Th17 cells in patients increases, especially in those patients who developed clinically relevant inflammatory and autoimmune toxicities." (PMID 29520282, 2018). "Transfer of in vitro-activated TILs8,9 and blockade of inhibitory receptors such as CTLA-4 and PD-1 have led to impressive results, with survival benefits in many cancers, including NSCLC3–6." (PMID 30504837, 2018). "Anti-CTLA-4 mAbs have been extensively studied in mouse models of cancer, where rejection of established tumors relies upon the impact of anti-CTLA-4 on CD4+ and CD8+ Teff and on CD4+FoxP3+ Treg cells." (PMID 29576375, 2018).
cancer (continued). "Cancer cells bind to co-inhibitory molecules on T cell surface such as CTLA-4, PD-1, TIM-3, and LAG-3 which in turn secrete immune-suppressive mediators such as IDO (indoleamine 2,3-dioxygenase) to create an immune subversive environment in the TME." (PMID 30081950, 2018). "Despite the successes of anti-CTLA-4 and ant-PD-1 therapies, these therapeutic modalities are capable of producing a durable response in a small subset of cancer patients." (PMID 29725606, 2018). "Although a subset of patients with advanced cancers experience durable remissions and prolonged survival in response to CTLA-4 or PD-1/PD-L1 checkpoint inhibitors, the majority of patients do not respond to such therapy." (PMID 29467463, 2018). "Based on the principle of CTLA4 function, approaches that reduce CTLA4 expression or inhibit its activity have been proposed for cancer immunotherapy." (PMID 29329591, 2018). "Although monoclonal antibodies (mAbs) against PD-1, such as Nivolumab or Pembrolizumab, are effective in some patients, the vast majority of cancers fail to respond to either PD-1 blockade or even dual checkpoint inhibition with a-CTLA-4 and a-PD-1." (PMID 29467463, 2018). "In 14 out of 17 patients, the diagnosis of CTLA-4 insufficiency was made prior the diagnosis of cancer." (PMID 30250467, 2018). "One of the reasons behind this observation is that patients with stage III cancer received higher dose of CTLA-4 (10 mg/kg), as approved for clinical use, compared to patients with stage IV cancer (3 mg/kg)." (PMID 29747688, 2018). "In cancer patients, anti-CTLA-4 treatment lowers the threshold required for T cell activation, which leads to an expansion of circulating low-avidity T cells, resulting in a sustained immune response." (PMID 29520282, 2018). "James Allison has relentlessly pursued anti-CTLA4 antibody for cancer immunotherapy and has been the champion leading the current IO revolution." (PMID 30577797, 2018). "Several mAbs targeting immune checkpoint molecules such as Cytotoxic T Lymphocyte Antigen-4 (CTLA-4), PD-1 and PD-L1 have been approved for the treatment of a broad spectrum of cancers." (PMID 30458852, 2018). "Immune checkpoint blockade with antibodies that target cytotoxic T lymphocyte-associated antigen 4 (CTLA-4) and the programmed cell death protein 1 pathway (PD-1/PD-L1) is leading to durable clinical responses in an increasing number of cancers." (PMID 30158830, 2018). "It was predicted that PD-1/PD-L1 blockade would have a greater anticancer effect than CTLA-4 inhibitors with fewer unwanted side effects due to the selective immunosuppressive signals delivered by cancer cells." (PMID 28866656, 2018). "Among the immune checkpoint inhibitors, PD-1/PD-L1 and CTLA-4 inhibitors showed promising therapeutic outcomes, and some have been approved for certain cancer treatments, while others are under clinical trials." (PMID 30546008, 2018). "There are indications in current literature identifying potential immunopathogenic rationales for CTLA-4 expression in certain cancers." (PMID 29672601, 2018). "A relevant mechanism that account for the progressive loss of immune function in cancer is the sustained signaling of multiple inhibitory receptors, commonly known as checkpoints, such as PD1 and CTLA-4, which down-regulate the antitumor immune response." (PMID 30619281, 2018). "Combination immunotherapy with PD-1/PD-L1 plus CTLA-4 checkpoint inhibitors has been studied in multiple cancer cell lines." (PMID 29769148, 2018). "Immune checkpoint inhibition using antibodies targeting CTLA4 and PD-1/PD-L1 is considered as a major breakthrough in cancer therapy in recent years." (PMID 30400822, 2018). "Ipilimumab and tremelimumab were the first anti-CTLA-4 antibodies to enter clinical trials in patients with advanced cancer." (PMID 30854331, 2018).
cancer (continued). "The two immune-checkpoint receptors that have been most actively studied in the context of clinical cancer immunotherapy, CTLA-4 and PD-1, regulate immune responses at different levels and by different mechanisms." (PMID 29482595, 2018). "Immune check-point inhibitors (i.e. anti PD-1 or anti CTLA-4 agents) have revolutionised cancer treatment in some diseases." (PMID 29599916, 2018). "Although this efficacy was limited to a few cancer cell lines that only responded to CTLA-4 when combined with a transduced granulocyte-macrophage colony-stimulating factor (GM-CSF) producing cellular vaccine." (PMID 28866656, 2018). "A majority of cancers fail to respond to immunotherapy with antibodies targeting immune checkpoints, such as cytotoxic T-lymphocyte antigen-4 (CTLA-4) or programmed death-1 (PD-1)/PD-1 ligand (PD-L1)." (PMID 29467463, 2018). "These immune-related genes include those that are established or promising targets for cancer immunotherapy such as CTLA4, PD1, PD-L1, PD-L2, IDO1, LAG3, and TIGIT." (PMID 30089500, 2018). "The results of our systematic review and meta-analysis indicate that treatment with ICIs improves prognosis in patients affected by different types of cancer, but with a higher benefit for men compared to women, especially when anti-CTLA-4 agents are used." (PMID 30545122, 2018). "Further studies on KIR genotype and cancer should focus on other treatment modalities, such as anti-CTLA4 treatment or NK cell therapy." (PMID 30374122, 2018). "Antibodies that block T cell inhibition via the immune checkpoints CTLA-4 and PD-1 have revolutionized cancer therapy during the last 15 years." (PMID 30233564, 2018). "As discussed here, HPV-related tumors require a great immune suppressor status for cancer development with increased activities of Treg, CTLA-4, and PD-1 and the suppression of APC and NK cells." (PMID 29854832, 2018). "By blocking immune checkpoints, including PD-1, PD-L1, and CTLA-4, with mAbs, the immune system can overcome the ability of cancer cells to oppose the immune responses, allowing for destruction of cancer cells." (PMID 30486519, 2018). "The anti-CTLA-4 antibody ipilimumab and anti-PD-1 antibodies pembrolizumab and nivolumab have been approved for cancer therapy in different countries." (PMID 30428588, 2018). "Much recent success in cancer clinical trials that blocked immune inhibitory signals, predominantly PD-L1, CTLA-4, and CD200 further underscored the importance of these inhibitory signals in reinvigorating the dysfunctional T cell responses." (PMID 29915577, 2018). "For example, Ad5/3-∆24-based OAd coding for anti-CTLA4 antibody has been tested in several cancer cell lines, and a direct anti-CTLA-4-mediated pro-apoptotic effect was observed in vitro and in vivo." (PMID 29614005, 2018). "Two humanized anti-CTLA-4 antibodies, Ipilimumab and Tremelimumab, have been approved as therapeutic options for the treatment of cancer." (PMID 29682521, 2018). "The clinical activity of the antibody for B7-H3-expressing cancers is currently under investigation, alone or in combination with monoclonal antibodies against either CTLA-4 or PD-L1." (PMID 30513627, 2018). "Immune checkpoint regulators, cytotoxic T lymphocyte antigen 4 (CTLA-4) and the programmed cell death protein-1/programmed death-ligand 1 (PD-1/PD-L1) have emerged as promising new targets for cancer therapeutics." (PMID 29672601, 2018). "In cancer, the microbiome also influences patient response to immune checkpoint inhibitors such as CTLA-4 and PD-1." (PMID 29701673, 2018). "First demonstrated in the treatment of patients with advanced melanoma, blockade of the CTLA-4 and PD-1 immune checkpoint pathways in the clinic generates an unprecedented survival benefit in some cancer patients." (PMID 29914571, 2018).
cancer (continued). "Checkpoint inhibitor (CPI) based immunotherapy (i.e., anit-CTLA-4/PD-1/PD-L1 antibodies) can effectively prolong overall survival of patients across several cancer types at the advanced stage." (PMID 30294272, 2018). "Among the many different immune checkpoints that regulate T-cell activation, cytotoxic T-lymphocyte-associated antigen 4 (CTLA4) and programmed cell death protein 1 (PD1) are the most well characterized and studied for cancer immunotherapy." (PMID 29301364, 2018). "Remarkably durable responses in subsets of cancer patients receiving CTLA-4 and PD-1/PD-L1 antibodies have driven fast-track approvals by the FDA for a range of malignancies, where long-lasting, extended survival times range from 24 to 45%." (PMID 30376867, 2018). "CTLA-4 is constitutively expressed on all cancer cells but found to be highly expressed on breast tumor cells and is implicated in immune dysregulation and associated with poor prognosis." (PMID 30622524, 2018). "Targeting CTLA-4 has shown remarkable long-term benefit and thus remains a valuable tool for cancer immunotherapy if the irAE can be brought under control." (PMID 29463898, 2018). "The first clinical development of a CTLA-4-blocking antibody, ipilimumab, proved that immune checkpoints would be attractive targets for cancer therapy." (PMID 30135516, 2018). "In tumors, T cells express a high level of CTLA-4, so that, cancer can evade the cytotoxic effect of T cells." (PMID 29371589, 2018). "For example, a common approach in cancer immunotherapy is controlling Treg function through a checkpoint blockade (e.g., anti–CTLA-4)." (PMID 30275967, 2018). "The strategy of combing HDAC inhibitors with an antibody targeting CTLA-4 is another potential approach to treat cancer." (PMID 30558227, 2018). "Immune checkpoint inhibitors (ICI) targeting CTLA-4 and the PD-1/PD-L1 axis have shown unprecedented clinical activity in several types of cancer and are rapidly transforming the practice of medical oncology." (PMID 29319049, 2018). "Based on CTLA4 and PD1 functions in different suppression pathways, a combination therapy of PD1 antibody and CTLA4 antibody, therefore, has emerged as an effective approach to combat cancers via checkpoint inhibition." (PMID 29329591, 2018). "Another important immunologic target for cancer immunotherapy after CTLA4 is programmed death 1 (PD1), a cell surface receptor that belongs to the immunoglobulin superfamily expressed only on activated T lymphocytes." (PMID 29329591, 2018). "The clinical success of specific immune checkpoint blockade, such as PD-1 and CTLA-4 (negative regulators of T-cell adaptive immune function), represent a promising advance in cancer immunotherapy development." (PMID 30483064, 2018). "Preclinical studies using monoclonal antibodies against CTLA-4 and/or PD-1 have shown promising results in some cancers, but unfortunately that was achieved in a small majority." (PMID 28388539, 2017). "We detected a significantly higher rate of PD-1 and CTLA-4 expression on TILs compared to PBMC of cancer patients with highly variable expression profiles on CD4+ and CD8+ cells." (PMID 28574843, 2017). "Specifically, expression of PD-1 in 71% (32/45) and CTLA-4 in 87% (39/45) cancer patients was higher than in all ten healthy adults." (PMID 28881603, 2017). "Recently, blockade of the immune checkpoints using monoclonal antibodies against cytotoxic T-lymphocyte antigen-4 (CTLA-4), PD-1, and PD-L1, has shown striking clinical results in cancer patients." (PMID 28881603, 2017). "PD-1 and CTLA-4 are expressed on a large proportion of tumour infiltrating lymphocytes in many different cancers." (PMID 30873473, 2017). "Immune checkpoint inhibitors, including antibodies against programmed death 1 (PD-1) and cytotoxic T-lymphocyte antigen 4 (CTLA-4), are being used with increasing frequency for the treatment of cancer." (PMID 28239462, 2017).